CAST (calpastatin )
Diseases named in the same sentence as CAST in open-access papers (continued):
Sharing a sentence is not in itself a finding about the gene and the disease.
pulmonary arterial hypertension (2 papers, 2019 to 2023). Pulmonary arterial hypertension (PAH) is a group of diseases characterized by mean pulmonary artery pressure >20 mmHg and elevated pulmonary arterial resistance leading to right heart failure. "Calpastatin is also a secreted molecule found in the synovial fluid of RA and OA patients, plasma of patients with pulmonary arterial hypertension, and exosomes from luminal fluid of ovine uterus." (PMID 36902150, 2023). "Calpastatin, the protein encoded by CAST, has an inhibiting effect on calpain and has been evoked in the progression of pulmonary hypertension." (PMID 31417607, 2019). "Interestingly, the differential expression of CAST and MCTP2, found in the present study, could be linked with two pathological phenotypes, pulmonary hypertension and overweight, both of which associated with CMS, as shown in the present study." (PMID 31417607, 2019).
sarcopenia (2 papers, 2022 to 2025). Progressive decline in muscle mass due to aging which results in decreased functional capacity of muscles. "CAST overexpression partially or completely prevented these alterations, highlighting a functional link between CAPN activity and CKD-associated sarcopenia." (PMID 41369335, 2025). "The involvement of CAPNs in CKD-related sarcopenia was assessed using mice that overexpressed the CAPNs endogenous inhibitor, calpastatin (CAST)." (PMID 41369335, 2025).
Sepsis (2 papers, 2010 to 2022). Sepsis is defined as life-threatening organ dysfunction caused by a dysregulated host response to infection. "Growing evidence suggests that the calpain/calpastatin system plays a critical role in the association between sepsis and multi-organ system dysfunction." (PMID 36160853, 2022). "Finally, one study has suggested that skeletal muscle calpain activation in sepsis is secondary, at least in part, to loss of activity of calpastatin, the endogenous calpain inhibitor." (PMID 20233404, 2010).
alcohol dependence (1 paper, 2013). Physical and psychological dependence on alcohol. "In a previous GWAS study, the SNP rs13160562 near CAST was discovered to besignificantly associated with alcohol dependence." (PMID 23876401, 2013).
ampullary carcinomas (1 paper, 2012). "When the ampullary and bile duct cohort was separated to cancers of the ampulla and cancers of the proximal and distal bile duct, low calpastatin expression was associated with survival in the ampullary cancers only (P = 0.043)." (PMID 23140395, 2012). "In the bile duct and ampullary carcinomas an association was observed between high cytoplasmic calpastatin expression and patients aged above 60 years (χ2=4.376, d.f.=1, P=0.036)." (PMID 23140395, 2012). "In the bile duct and ampullary cancer cohort, low cytoplasmic calpastatin expression was associated with adverse overall survival (P=0.012), which remained significant in multivariate analysis (P=0.037)." (PMID 23140395, 2012). "In bile duct and ampullary carcinomas an association was observed between cytoplasmic calpastatin expression and patient age (P = 0.036), and between nuclear calpastatin expression and increased tumour stage (P = 0.026) and the presence of vascular invasion (P = 0.043)." (PMID 23140395, 2012). "The expression of calpain-1, calpain-2 and calpastatin cytoplasmic and nuclear expression was tested to determine associations with clinicopathological criteria in the pancreatic and the grouped bile duct and ampullary cancers." (PMID 23140395, 2012). "The aims of the current study were to investigate the expression levels of calpastatin, and of the catalytic subunits of μ-calpain and m-calpain in tumours from pancreatic, bile duct and ampullary cancer patients." (PMID 23140395, 2012). "In the bile duct and ampullary carcinomas calpain-1 expression had a statistically significant correlation with cytoplasmic calpastatin expression (r = 0.425, P < 0.001) and nuclear calpastatin expression (r = 0.295, P = 0.002), but not with calpain-2 expression." (PMID 23140395, 2012).
aneurysm (1 paper, 2024). Bulging or ballooning in an area of an artery secondary to arterial wall weakening. "Recently, it has been demonstrated that the expression of calpain was increased in aneurysm tissues obtained from Marfan syndrome patients, whereas calpastatin was decreased." (PMID 39590217, 2024).
Aortic Rupture (1 paper, 2025). The tearing or bursting of the wall along any portion of the AORTA, such as thoracic or abdominal. "As expected, calpastatin overexpression significantly reduced mortality associated with aortic rupture." (PMID 40171827, 2025).
Ataxia (1 paper, 2011). Ataxia refers to impaired coordination of voluntary muscle movement. "Conversely, several mice displayed a weak ERP, as evidenced by a body temperature greater than 34°C and mild walking ataxia score, despite retaining homozygous CAST/Ei alleles over a significant fraction of the critical region." (PMID 22241984, 2011).
atherosclerosis (1 paper, 2014). A disease characterized by the build-up of fatty material and calcium deposition in the arterial wall resulting in partial or complete occlusion of the arterial lumen. "We detected one locus on Chromosome 6 for atherosclerosis that maps within the 95% confidence interval of a previously reported QTL, Ath37, which was identified in studies using sub-congenic mice between C57BL/6J and CAST/EiJ." (PMID 25344410, 2014).
Atrophy (1 paper, 2008). Any weakening or degeneration, especially through lack of use. "Since NF-H, MAP2 and myelin basic protein (MBP) are substrates of calpain, and calpain is known to be involved in Aβ-induced axonal atrophy, expression levels of calpain and calpastatin were measured." (PMID 18706097, 2008).
blastomycosis (1 paper, 2022). Blastomycosis is a rare infection that may develop when people inhale a fungus called Blastomyces dermatitidis, a fungus that is found in moist soil, particularly where there is rotting vegetation. "In this work, we describe wide natural variation in both primary and acquired resistance to experimental pulmonary blastomycosis in eight founder strains, including 129, A/J, BL/6, CAST, NOD, NZO, PWK, and WSB of the Collaborative Cross collection, and the inbred DBA strain." (PMID 35089087, 2022).
Cachexia (1 paper, 2023). Severe weight loss, wasting of muscle, loss of appetite, and general debility related to a chronic disease. "An in vitro cachexia model using liver cancer cells and a C26 colon cancer study demonstrated that Calpain-1 was highly upregulated in these cells, which was opposite to the calpastatin level, and the Ca2 + -dependent proteolytic pathway was highly activated in the C26 cachexia rat model." (PMID 37217930, 2023).
celiac disease (1 paper, 2019). An autoimmune genetic disorder with an unknown pattern of inheritance that primarily affects the digestive tract. "On the other hand, the top non-HLA DMRs in celiac disease mapped to genes related to the immune response, including NLRC5 and TMEM105 in the epithelial fraction, and CAST and HOXC4 in the immune compartment." (PMID 30718669, 2019).
Cerebral ischemia (1 paper, 2023). Restriction of arterial blood supply to the brain associated with insufficient oxygenation to support the metabolic requirements of the tissue. "CAST expression has been shown to have a neuroprotective effect on cerebral ischemia." (PMID 36855067, 2023).
clear-cell carcinoma (1 paper, 2019). "High calpastatin expression was associated with younger patients (χ2 = 4.955, df = 1, P = 0.026) and high-grade serous carcinoma (HGSC) (χ2 = 17.403, df = 5, P = 0.004) whilst low calpastatin expression was linked with clear-cell carcinoma (CCC)." (PMID 30448882, 2019).
colon cancer (1 paper, 2020). "For this purpose, we compared the expression levels of CAPN1, CAPN2, CAPNS1 and CAST in different cell lines and chose human HCT116 colon cancer cells." (PMID 33078830, 2020). "HCT116 have increased levels of CAPN2 in comparison with other colon cancer cell lines, and we also confirmed that protein levels of CAPN1 and CAPN2 are significantly higher than those in HeLa or HEK293 cells while the amount of CAST is moderate." (PMID 33078830, 2020).
cyst (1 paper, 2015). A sac-like closed membranous structure that may be empty or contain fluid or amorphous material. "We have also generated a derivative congenic line with a refined CAST-derived Mpkd1-2 interval and demonstrated its dominantly-acting disease-modulating effects (e.g., 4.2-fold increase in total cyst area; p<0.001)." (PMID 26295839, 2015).
demyelinating disease (1 paper, 2022). A broad group of disorders that affect the myelin sheaths that cover the neurons. "Our results suggest that the calpain-calpastatin system has putative roles in myelination and demyelinating diseases of peripheral nerves." (PMID 36499770, 2022). "As a first step in examining calpains’ potential role in peripheral demyelinating diseases, we here characterize the calpains and calpastatin during postnatal development, in a chronic model when normal myelination is disrupted, and in an acute demyelinating model." (PMID 36499770, 2022).
E. coli infection (1 paper, 2020). "E. coli infection resulted in the upregulation of the genes encoding proteases, which participate in the degradation of ECM, namely, ADAM10 (logFC of 2.62), ADAM17 (logFC of 8.75), MMP9 and MMP14 (both with a logFC of 2.58), CAPN7 and CAST (both with logFC of 2.20)." (PMID 32234079, 2020).
Erythema (1 paper, 2020). Redness of the skin, caused by hyperemia of the capillaries in the lower layers of the skin. "In this study we wanted to evaluate if CAST/EiJ mice could serve as a suitable model to study VARV infection and whether the presentation of the subjective clinical signs (including reduced grooming, weight loss, decreased activity, ocular and nasal swelling, and erythema) were dose dependent." (PMID 31593747, 2020).
HCMV infection (1 paper, 2019).
Hyperglycemia (1 paper, 2015). An increased concentration of glucose in the blood. "Given the very recent study reporting that overexpression of calpastatin improved EDHF-mediated ED in the aorta of mice with hyperglycemia." (PMID 26120352, 2015).
hyperhomocysteinemia (1 paper, 2025). A serious metabolic condition caused by mutations in the MTHFR gene, medications, or nutritional deficiency. "In models of MASLD induced by hyperhomocysteinemia, CAST reduction was associated with increased calpain activity, which resulted in the degradation of the inhibitor kappa B alpha (IκBα)." (PMID 41468440, 2025). "Hyperhomocysteinemia also induces MASLD associated with increased calpain activity and reduced CAST levels." (PMID 41468440, 2025).
Infertility (1 paper, 2024). "Since further backcrossing of the Kif18agcd2 allele onto the CAST genetic background ultimately leads to more pronounced infertility, it is likely that multiple divergent CAST alleles with additive or epistatic interactions ultimately exacerbate germ cell depletion." (PMID 39677807, 2024). "Subsequent backcrossing of F2 mice to the CAST background increased the penetrance of infertility to 90%, while subsequent backcrossing to B6 decreased the penetrance to just over 37%." (PMID 39677807, 2024). "We found that CAST mice, which exhibit high penetrance of infertility in the absence of Kif18a, had significantly higher expression of Apc7 in juvenile and adult testicular tissue, as well as reduced expression of Apc5 in fetal ovarian tissue compared to B6 mice." (PMID 39677807, 2024).
inflammatory breast carcinoma (1 paper, 2016). An advanced, invasive breast adenocarcinoma characterized by the presence of distinct changes in the overlying skin. "Perhaps the most interesting observation is that of calpastatin expression, whereby high expression is associated with improved survival of inflammatory breast cancer and high expression is associated with adverse survival of non-inflammatory breast cancer." (PMID 27323818, 2016). "This study demonstrates that high calpastatin expression in the diagnostic core biopsy was significantly associated with improved survival in patients with inflammatory breast cancer, while the reverse was observed in non-inflammatory cases." (PMID 27323818, 2016).
invasive breast carcinoma (1 paper, 2016). A carcinoma that infiltrates the breast parenchyma. "In early invasive breast cancer expression of calpain-1, calpain-2 and their inhibitor, calpastatin, have been associated with clinical outcome and clinicopathological factors." (PMID 27323818, 2016).
ischemia (1 paper, 2022). A hypoperfusion of the BLOOD through an organ or tissue caused by a PATHOLOGIC CONSTRICTION or obstruction of its BLOOD VESSELS, or an absence of BLOOD CIRCULATION. "Previous studies have shown that calpastatin is downregulated in heart and brain tissue after ischemia-reperfusion injury." (PMID 35723325, 2022). "Overexpression of calpastatin and thus secretion could potentially have a protective effect against IRI; and targeting calpains during NMP could possibly protect the kidney against ischemia." (PMID 35723325, 2022).
mood disorder (1 paper, 2020). A cognitive disorder a disturbance in which the person's mood is hypothesized to be the main underlying feature. "The results of the sucrose preference test suggest that CAST KO dams are susceptible to pregnancy and postpartum mood disorder, which increases the risk for pup neglect." (PMID 32251313, 2020).
multiple sclerosis (1 paper, 2021). A progressive autoimmune disorder affecting the central nervous system resulting in demyelination. "Further analysis of diseases and functions found that in comparison with B6, CAST show a downregulation in pathways relevant to “multiple sclerosis,” “inflammatory demyelinating disease,” and “extravasation of cells”." (PMID 33567283, 2021).
Myocardial fibrosis (1 paper, 2015). "Overexpression of CAST significantly reduced the infarct size (P < 0.01) and blunted MI-induced interventricular hypertrophy, global myocardial fibrosis and collagen I and collagen III deposition, hypotension and hemodynamic disturbances at 21 days after MI." (PMID 25786109, 2015).
nasopharyngeal carcinoma (1 paper, 2020). A carcinoma arising from the nasopharyngeal epithelium. "For example, the endogenous inhibitor of CAPN protein, calpastatin, is downregulated in nasopharyngeal carcinoma." (PMID 32382656, 2020).
neuropathy (1 paper, 2022). A disorder affecting the nervous system that manifests with pain, tingling, numbness, and/or muscle weakness. "To examine the calpain-calpastatin system in the inherited neuropathy with dysmyelination, we collected sciatic nerves from wild-type (WT) and Tr-J mice at 8 weeks of age." (PMID 36499770, 2022).
osteoporosis (1 paper, 2023). A condition of reduced bone mass, with decreased cortical thickness and a decrease in the number and size of the trabeculae of cancellous bone (but normal chemical composition), resulting in increased fracture incidence. "This novel osteocyte-secreted-calpastatin mechanism could be therapeutically leveraged to treat osteoporosis in women." (PMID 36902150, 2023).
Ovarian tumours (1 paper, 2012). "Ovarian tumours of the serous type were associated with high expression of calpastatin (χ2 = 23.755, d.f. = 4, P < 0.001), high calpain-1 (χ2=15.961, d.f. = 4, P = 0.003) and high calpain-2 (χ2 = 26.02, d.f. = 4, P < 0.001)." (PMID 22435971, 2012).
Parkinson disease (1 paper, 2013). A progressive degenerative disorder of the central nervous system characterized by loss of dopamine producing neurons in the substantia nigra and the presence of Lewy bodies in the substantia nigra and locus coeruleus. "The main finding of this study is a lack of a significant association between the CAST gene and late-onset sporadic Parkinson’s disease in the Han Chinese population." (PMID 23951044, 2013).
prostate carcinoma (1 paper, 2018). A carcinoma that arises from epithelial cells of the prostate gland. "Other proteins such as the androgen receptor (AR), which is required for growth in both androgen-sensitive and androgen-insensitive prostate cancer are cleaved by calpain in the presence of high Ca2+ concentrations due to the release of calpain from the calpain-CaM-calpastatin complex." (PMID 30319995, 2018).
protein misfolding diseases (1 paper, 2023). "Thus, in protein misfolding diseases or disorders characterized by abnormal Ca2+ regulation, strategies to limit the effects of calpain activation are primarily based on calpastatin." (PMID 36984009, 2023).
renal dysfunction (1 paper, 2020). "We found that endothelial-specific Capn4 knockout and calpastatin overexpression alleviated renal dysfunction in endotoxemic mice." (PMID 32346126, 2020).
retinal disease (1 paper, 2011). "Rationale for the retinal disease pathway was based on findings that genetic alterations specific to CAST/EiJ have been shown to be potentially involved in the development of age related macular degeneration (AMD)." (PMID 21779340, 2011).
retinitis pigmentosa (1 paper, 2023). Retinitis pigmentosa (RP) is an inherited retinal dystrophy leading to progressive loss of the photoreceptors and retinal pigment epithelium and resulting in blindness usually after several decades. "The remodeling of photoreceptors caused by CAST and ELKS ablation in the mature retina sheds light on the previously unknown mechanisms of retinitis pigmentosa, a retinal disorder, with both sporadic and inherited cases, characterized by the degeneration of rod photoreceptors." (PMID 37108413, 2023).
substance dependence (1 paper, 2015). The psychological or physiological need to take a substance in order to experience its effects or to avoid the effects of its absence. "However, it was not correlated to risks of substance dependence (scores of AUDIT-C, HSI, and CAST)." (PMID 25972826, 2015).
systemic lupus erythematosus (1 paper, 2025). An autoimmune multi-organ disease typically associated with vasculopathy and autoantibody production. "Moreover, RA patients develop calpastatin autoantibodies, and their incidence is higher than in other patients with systemic autoimmune diseases, such as systemic lupus erythematosus (SLE, 27%), polymyositis/dermatomyositis (24%), systemic sclerosis (38%), and overlap syndrome (29%)." (PMID 41294867, 2025).
Tremor (1 paper, 2015). An unintentional, oscillating to-and-fro muscle movement about a joint axis. "Overexpression of CAST delayed the age of onset of tremors in the HD mice." (PMID 25257175, 2015). "Furthermore, we show that overexpression of CAST in mice results in enhanced autophagy and improves locomotor function and delays tremor onset in a mouse model of HD, as well as decreasing the number of Htt aggregates seen in the brain." (PMID 25257175, 2015).
uremia (1 paper, 2025). A clinical syndrome associated with the retention of renal waste products or uremic toxins in the blood. "However, mice overexpressing CAST showed significantly reduced fibrotic areas and lower fibronectin expression, suggesting that CAST overexpression may delay uremia-induced fibrosis." (PMID 41369335, 2025).